GSK3B (glycogen synthase kinase 3 beta)
Diseases named in the same sentence as GSK3B in open-access papers (continued):
Sharing a sentence is not in itself a finding about the gene and the disease.
cardiac hypertrophy (continued). "A previous study has shown that the overexpression of constitutively active GSK-3β in cultured cardiomyocytes attenuate cardiac hypertrophy induced by hypertrophic agents such as ET-1 and phenylephrine by blocking the NFAT nuclear translocation." (PMID 37033243, 2023). "To investigate the molecular mechanisms underlying TAC-induced cardiac dysfunction in Ogt-Tg mice, we examined the GSK-3β and NF-κB signaling pathways that are involved in cardiac hypertrophy." (PMID 37033243, 2023). "Collectively, our results delineated that ANGPTL8 ameliorated the development of pathological cardiac hypertrophy via the LILRB3-Akt/GSK3β signaling cascade." (PMID 35851270, 2022). "In summary, ANGPTL8, which binds to LILRB3, negatively regulates the development of pathological cardiac hypertrophy by inhibiting Akt/GSK3β activity." (PMID 35851270, 2022). "Mhrt779 inhibited the activation of the histone deacetylase 2 (HDAC2)/Akt/GSK3β pathway during pathological cardiac hypertrophy." (PMID 35461308, 2022). "Taken together, these results indicated that secreted ANGPTL8 ameliorated cardiac hypertrophy by binding to the membrane receptor PIRB (LILRB3) to suppress Akt/GSK3β activity." (PMID 35851270, 2022). "One of the known downstream effectors of AKT, glycogen synthase kinase-3β (GSK-3β), negatively regulates cardiac hypertrophy." (PMID 35151687, 2022). "ANGPTL8 exerts a cardioprotective effect on pathological cardiac hypertrophy by negatively regulating the Akt/GSK3β signaling pathway." (PMID 35851270, 2022). "The p38/JNK1/2 and AKT/GSK3β signalling pathways are downstream targets of TAK1 and are implicated in cardiac hypertrophy and heart failure." (PMID 35096272, 2022). "Treatment of mice overexpressing Hdac2 with TSA increases GSK3β and following INPP5f activity, which prevents cardiac hypertrophy." (PMID 35958418, 2022). "The role of GSK3β S9 in cardiac hypertrophy and remodeling has been studied in different in vivo models, including myocardial infarction and TAC." (PMID 34948382, 2021). "Our previous study, e.g., showed that miR-21-3p suppressed HDAC8 expression and decreased phospho-Akt and phospho-Gsk3β expression to attenuate cardiac hypertrophy." (PMID 34368265, 2021). "The phosphorylation of AKT also inactivates GSK-3β, an essential negative regulator of cardiac hypertrophy and cardiomyopathy." (PMID 34604360, 2021). "Prior studies show that glycogen synthase kinase 3β (GSK3β) contributes to cardiac ischemic injury and cardiac hypertrophy." (PMID 34948382, 2021). "Mechanistically, Akt1 directly promotes protein translation, in part by inhibiting GSK3β activity, which negatively regulates eukaryotic translation initiation factor 2B and thereby represses cardiac hypertrophy." (PMID 33400052, 2021). "GSK3β is constitutively expressed in cardiac myocytes and was among the first negative regulators of cardiac hypertrophy to be identified." (PMID 33400052, 2021). "Among the 18 mammalian HDACs, HDAC2 acts as a pro-hypertrophic regulator of cardiac hypertrophy development by modulating the GSK3β or kruppёl like factor 4 activity." (PMID 33959033, 2021). "The authors also showed that HDAC8 regulates cardiac hypertrophy via the Akt/GSK3β pathway, further supporting our findings." (PMID 33959033, 2021). "Glycogen synthase kinase-3β (GSK-3β) is a serine/threonine kinase and a negative regulator of cardiac hypertrophy." (PMID 34778891, 2021). "Global deletion of GSK3β exacerbates myocardial hypertrophy possibly due to hyperproliferation of cardiomyoblast." (PMID 34381779, 2021). "GSK3β overexpression significantly reversed the expression of cardiac hypertrophy-related markers including ANP, ACTA1 and MYH7." (PMID 33240671, 2020). "Our study revealed that miR-26a-5p promotes myocardial cell autophagy activation and cardiac hypertrophy by regulating GSK3β, which needs further research." (PMID 33240671, 2020).
cardiac hypertrophy (continued). "Activated GSK-3β in diabetic rats reduces diastolic and systolic myocardial function and aggravates cardiac hypertrophy, correlated with excessive collagen accumulation." (PMID 33052244, 2020). "DM-celecoxib can control cardiac hypertrophy and myocardial fibrosis caused by TAC by activating GSK-3β." (PMID 33052244, 2020). "The GSK3β cytokine downstream of PI3KAkt, which can be inactivated by phosphorylation, is a key negative regulator of cardiac hypertrophy." (PMID 33273955, 2020). "GSK3β overexpression remarkedly decreased miR-26a-5p-induced increase in cardiac hypertrophy-related marker expression." (PMID 33240671, 2020). "At the mRNA and protein levels, the expression of GSK3β was decreased in PE-induced cardiac hypertrophy compared to control group." (PMID 33240671, 2020). "Cathepsin L (CTSL) blocks cardiac hypertrophy and improves cardiac function by activating GSK-3β in rat neonatal cardiac myocytes." (PMID 33052244, 2020). "According to above results, miR-26a-5p inhibited antihypertrophic GSK3β expression in PE-induced cardiac hypertrophy in vitro." (PMID 33240671, 2020). "Inhibiting SLC26A4 significantly elevated the mRNA expression of GSK-3β in PE-induced cardiac hypertrophy models." (PMID 31998553, 2020). "In our study, miR-26a-5p was up-regulated in PE-induced cardiac hypertrophy, furthermore, high miR-26a expression promoted myocardial cell autophagy activation and cardiac hypertrophy by GSK3β." (PMID 33240671, 2020). "We have also reported that cardiac fibroblast -specific deletion of GSK-3β leads to pathological cardiac hypertrophy in ischemic hearts." (PMID 32365965, 2020). "Taken together, these studies suggest that GSK-3β mediated regulation of cardiac hypertrophy is specific to the employed stress, as well as to cell-specific gene targeting." (PMID 32365965, 2020). "The results revealed that highly expressed miR-26a-5p promoted myocardial cell autophagy activation and cardiac hypertrophy in rat hearts by regulating GSK3β." (PMID 33240671, 2020). "For example, previous research has found that overexpressed cardiac-specific Traf2 enhances cardiac hypertrophy by activating AKT/GSK3β signaling pathway." (PMID 31998553, 2020). "Our results revealed that GSK3β expression was inhibited in PE-induced cardiac hypertrophy treated by miR-26a agomir, which was consistent with previous studies." (PMID 33240671, 2020). "Growing studies suggest that GSK-3β negatively regulates cardiac hypertrophy, and inhibits GSK3β via hypertrophic stimulation contributes to cardiac hypertrophy." (PMID 33240671, 2020). "To further assess the function of miR-26a-5p in cardiac hypertrophy, we tested cardiac hypertrophy related marker protein GSK3β (a negative regulator of cardiac hypertrophy) expression." (PMID 33240671, 2020). "Consistent with the results in vitro, siRNA-SLC26A4 inhibited ANP and BNP and promoted GSK3β accumulation in cardiac hypertrophy mice." (PMID 31998553, 2020). "In cardiac hypertrophy, miR-26a was down-regulated while overexpression of miR-26a can inhibit the process of myocardial hypertrophy via decreasing GSK3β expression." (PMID 32955094, 2020). "Taken together, both Akt and GSK3β are important mediators of pregnancy-induced cardiac hypertrophy." (PMID 32252821, 2020). "Cardiac hypertrophy was accompanied by transient phosphorylation and inactivation of GSK3β, which promotes LV hypertrophy and enhances resistance of cardiomyocytes to oxidative stress." (PMID 30765322, 2019). "In contrast to other deubiquitinating enzymes, USP14 has demonstrated to induce cardiac hypertrophy via enhancing GSK-3β phosphorylation, suggesting that USP14 can be potentially developed as a therapeutic target against cardiac hypertrophy." (PMID 30186311, 2018). "Phosphorylated glycogen synthase kinase (GSK)-3β and serine/threonine kinase (AKT) are associated with cardiac hypertrophy." (PMID 30417024, 2018).
cardiac hypertrophy (continued). "Many studies have shown that the stress-induced activation of Gsk-3β and the resulting induction of cardiac hypertrophy are deleterious." (PMID 29611541, 2017). "The results of our lab work indicate that inhibition of AKT/GSK3β obviously attenuates pressure overload-induced cardiac hypertrophy." (PMID 28127304, 2017). "Here, we investigated the effect of RES on ERK 1/2, p38-MAPK, Akt-1, and GSK-3β pathways which plays a critical role in cardiac hypertrophy and ventricular dilatation, myocyte survival, apoptosis, autophagy, and necrosis." (PMID 29109832, 2017). "AKT also resulted in the inactivation of GSK-3β and contributed to the process of cardiac hypertrophy." (PMID 28127304, 2017). "The data from our previous studies demonstrated that inhibition of AKT/GSK3β alleviated AB-induced cardiac hypertrophy." (PMID 27110236, 2016). "Increasing evidence shows that GSK3β serves as an essential negative regulator of cardiac hypertrophy and is involved in the setting of heart ischemic injury." (PMID 26918336, 2016). "Activated AKT phosphorylates and inactivates the downstream GSK3β signaling, further promoting the development of pathological cardiac hypertrophy." (PMID 27110236, 2016). "GSK-3β has been described as a negative regulator of cardiac hypertrophy induced by endothelin-1, insulin-like growth factor 1, β-adrenergic agonists, and pressure overload." (PMID 27977752, 2016). "Our preliminary results demonstrated that low-dose TU increased the mRNA expression of GSK-3β and SERCA2a, possibly affecting myocardial hypertrophy." (PMID 25780423, 2015). "GSK-3β is important negative regulator of cardiac hypertrophy and plays an important role in the regulation of myocardial apoptosis." (PMID 25780423, 2015). "Taking into account the critical role of Akt/GSK-3β in regulation the progress of both cardiac hypertrophy and cell cycle, we next examined the activation of this signaling pathway." (PMID 24763737, 2014). "PTEN must be inactivated to increase cellular levels of PIP3 for recruiting downstream signaling molecules, such as Akt, and inhibiting GSK-3β, whose inactivation plays a vital role in the development of cardiac hypertrophy." (PMID 24971153, 2014). "PTEN is a phosphatase that acts as a negative regulator of the Akt/GSK-3β pathway and plays a vital role in cardiac hypertrophy." (PMID 24971153, 2014). "In this context we found that TWEAK treatment after MI resulted in an overall reduced activation of different protective mediators of cardiac hypertrophy like Akt, GSK3β, or ERK1/2." (PMID 24692845, 2014). "ß-catenin degradation is initiated following phosphorylation by glycogen synthase kinase 3 beta (GSK3ß), a kinase counteracting cardiac hypertrophy, inhibiting apoptosis and fibrosis and thus increasing cardiac contractility." (PMID 22905262, 2012). "Cardiac hypertrophy is facilitated by decreased activity of the glycogen synthase kinase-3 beta (GSK3ß), which in turn leads to enhanced ß-catenin abundance." (PMID 22905262, 2012). "GSK3β is shown to inhibit cardiac hypertrophy by preventing the nuclear translocation of nuclear factor of activated T-cells (NFATc3) via the phosphorylation of NFATc3." (PMID 22043204, 2010). "p38MAPK and GSK-3β act as a negative regulators of cardiac hypertrophy, rephosphorylating NFAT and promoting its export from the nucleus." (PMID 20502695, 2010). "There are increasing lines of evidence that GSK3B is an essential negative regulator of cardiac hypertrophy and that the inhibition of GSK3B by hypertrophic stimuli is an important mechanism contributing to the development of cardiac hypertrophy." (PMID 19629191, 2009). "Apart from acting as an anti-apoptotic factor, Akt is a major repressor of cardiac hypertrophy by inhibitory phosphorylation of GSK3β." (PMID 19936192, 2008). "In summary, our findings underscore the emerging evidence of MEK/Erks and Akt/GSK3β in the pathogenesis and regulation of cardiac hypertrophy." (PMID 19936192, 2008).
cardiac hypertrophy (continued). "As lipid emulsion alone increased GSK-3β phosphorylation, which may lead to enhanced cardiac hypertrophy, further examination of the effect of lipid emulsion on the hypertrophic signal pathway in the heart is needed." (PMID 39936979, 2025). "Therefore, our findings suggest that LIMD1 improves outcomes in post-HF pathological cardiac hypertrophy by targeting the YAP1/AKT/GSK3β signaling pathway." (PMID 39937832, 2025). "Similarly, S-nitrosylation of HSP90 enhances its interaction with GSK-3β, leading to increased GSK-3β phosphorylation and the reduced phosphorylation of its downstream target, eIF2Bε, thereby accelerating cardiac hypertrophy." (PMID 40867518, 2025). "The active form of GSK-3β (non-phosphorylated) is involved in the inhibition of cellular signal pathways associated with cardiac hypertrophy." (PMID 39936979, 2025). "The YAP1/AKT/GSK3β signaling pathway plays a significant role in cardiac hypertrophy." (PMID 39937832, 2025). "Moreover, the O-GlcNACylation of GSK-3β at Ser9 was increased, and the O-GlcNAcylation of GSK-3β caused compensatory cardiac hypertrophy to mediate increased O-GlcNAcylation-aggravated pressure-overload-induced heart failure." (PMID 38790676, 2024). "GSK-3β induces cardiac hypertrophy by promoting NFAT nuclear translocation." (PMID 39451203, 2024). "Secondly, phosphorylated glycogen synthase kinase 3β (GSK-3β) may stimulate cardiac hypertrophy, which was regulated by activated -RAC-alpha serine/threonine-protein kinase (AKT)." (PMID 37469482, 2023). "Some studies have shown that the increased expression of HSP90 leads to increased phosphorylation of GSK3β and decreased phosphorylation of eIF2Bε, thereby aggravating cardiac hypertrophy and the accumulation of HSP90 accelerates vascular remodeling in hypertensive arterial smooth muscle cells." (PMID 37115066, 2023). "However, the inhibitory effects of Trim44 KO on pathological cardiac hypertrophy induced by ISO treatment were exerted by suppressing the AKT/mTOR/GSK3β/P70S6K signaling pathway." (PMID 35855640, 2023). "Cardiac hypertrophy-associated PIWI-interacting RNA (CHAPIR) competitively binds METTL3 and blocks m6A methylation of polymerase family member 10 (PARP10), while up-regulation of PARP10 facilitates glycogen synthesis and pathological cardiac hypertrophy by inhibiting the kinase activity of GSK-3β." (PMID 36830642, 2023). "Studies have confirmed that overexpression of GSK-3β has a crucial effect on myocardial hypertrophy, including the suppression of protein synthesis and the expression of hypertrophic genes, while inhibition of GSK-3β can lead to aggravation of myocardial hypertrophy." (PMID 36788811, 2023). "Promisingly, inhibiting the AKT/GSK-3β pathway may attenuate myocardial hypertrophy induced by pressure overload." (PMID 37469482, 2023). "Moreover, the activation of Akt can inhibit GSK3β (GSK3β is an inhibitor of myocardial hypertrophy), and it will activate the expression of other genes related to myocardial hypertrophy." (PMID 36834623, 2023). "In this study, cardiac hypertrophy in HFpEF rats may be associated with PI3K/AKT signaling pathway activation, further inhibiting GSK-3β activation." (PMID 37469482, 2023). "The results suggested that the PI3K/AKT pathway might promote myocardial hypertrophy by regulating GSK-3β phosphorylation in HFpEF rats." (PMID 37469482, 2023). "Accumulated evidence has shown that gradually increasing Akt/GSK3β levels could play a crucial role in the process of cardiac hypertrophy from compensatory to decompensatory." (PMID 35851270, 2022). "Researches have shown that GSK-3β aggravated cardiac hypertrophy and heart failure." (PMID 36164369, 2022). "All the results supported that ANGPTL8 regulated cardiac hypertrophy via the Akt/GSK-3β pathway." (PMID 35851270, 2022).
cardiac hypertrophy (continued). "Cyclic guanosine monophosphate (cGMP), as a second messenger, negatively regulates the secretion of ANP, and the cGMP-mediated Akt/GSK-3β signaling pathway has been shown to be closely related to cardiac electrophysiology, myocardial hypertrophy, and myocardial contraction." (PMID 36060704, 2022). "GSK-3β can regulate cardiac hypertrophy and cardiac fibrosis." (PMID 36237833, 2022). "The Akt/GSK-3β signaling pathway is known to be critically involved in various pathological processes of the heart, including myocardial fibrosis, myocardial hypertrophy, and ischemia-reperfusion injury." (PMID 36060704, 2022). "Data from our studies with isolated cardiomyocytes suggest that the noted increase in GSK3β S389 phosphorylation may counteract the development of cardiac hypertrophy in the diseased myocardium." (PMID 34948382, 2021). "Dioscin improves cardiac hypertrophy by inhibiting the Akt/GSK3β/mTOR pathway." (PMID 33778070, 2021). "It was reported that miRNAs could target GSK3β in some cardiac pathological processes, such as myocardial I/R injury, cardiac hypertrophy, and cardiac fibrosis, which suggested that miRNAs might be involved in glycogen synthesis." (PMID 34368265, 2021). "Other studies have shown that plantamajoside, an extract of Plantaginis Herba, can inhibit the activation of histone deacetylase 2 (HDAC2), and the transduction of downstream signals, AKT/GSK-3β, in turn has an important protective effect against cardiac hypertrophy." (PMID 33897800, 2021). "There is growing evidence that GSK-3β is an important regulator of cardiac hypertrophy." (PMID 31998553, 2020). "GSK3β could remarkedly reversed miR-26a-5p-induced increase in cardiac hypertrophy-related marker expression." (PMID 33240671, 2020). "Now, many TNF-dependent genes linked to ECM remodeling as well as AF are upregulated with exercise in WT atria compared to sedentary, including Mmp14, Fgf2 (i.e., fibroblast growth factor 2, which activates p38 and induces cardiac hypertrophy as well as fibrosis), Gsk3β, and Tln1." (PMID 33424629, 2020). "Therefore, high miR-26a-5p expression inhibited GSK3β expression and promoted cardiac hypertrophy in vivo." (PMID 33240671, 2020). "MiR-199a targets the glycogen synthase kinase 3β (GSK3β)/mammalian target of rapamycin (mTOR) complex signaling pathway to impair cardiomyocyte autophagy and thereby enhancing cardiac hypertrophy (miR-199a impairs autophagy and induces cardiac hypertrophy through mTOR activation)." (PMID 33392270, 2020). "Furthermore, silencing GSK3β significantly reversed miR-26a-5p inhibitor-induced decrease in cardiac hypertrophy-related marker expression in PE-induced H9C2 cells." (PMID 33240671, 2020). "However, siRNA-SLC26A4 significantly promoted the expression level of GSK-3β in PE-induced cardiac hypertrophy models." (PMID 31998553, 2020). "We have reported the stress-specific role of GSK-3β on cardiac hypertrophy." (PMID 32365965, 2020). "Previous study has found that GSK-3β activation was involved in the process of cardiac hypertrophy." (PMID 31998553, 2020). "Therefore, above results suggested that miR-26a-5p inhibited GSK3β expression and promoted cardiac hypertrophy in vivo." (PMID 33240671, 2020). "We also observed the expression of ANP, BNP and GSK-3β in cardiac hypertrophy models in vivo." (PMID 31998553, 2020). "USP14 promotes the progression of cardiac hypertrophy by increasing GSK-3β phosphorylation." (PMID 32471496, 2020).